DEFB125 (defensin beta 125)
Description:
Has antibacterial activity.
Synonyms: DEFB-25
Tractability: Antibody: UniProt places it where antibodies can reach, with high confidence; UniProt predicts a signal peptide or a membrane-spanning region; its Gene Ontology location is reachable by antibodies, with medium confidence.
Gene: Protein-coding gene on chromosome 20 (87,250 to 97,094, forward strand). Ensembl gene ENSG00000178591.
Subcellular location: Secreted
Pathways (Reactome):
Immune System: Beta defensins; Defensins
Gene Ontology:
Molecular function: membrane destabilizing activity
Biological process: innate immune response; killing of cells of another organism; defense response to Gram-negative bacterium
Cellular component: extracellular region
Genetic constraint (gnomAD): Loss-of-function variants: 1 observed, 2.81 expected, observed/expected ratio (o/e) 0.36, 90% interval 0.12 to 1.53. That is too few expected variants to judge how well the gene tolerates losing a copy. Missense variants: 61 observed, 65.93 expected, observed/expected ratio (o/e) 0.93, 90% interval 0.75 to 1.14. Synonymous variants: 22 observed, 23.98 expected, observed/expected ratio (o/e) 0.92, 90% interval 0.65 to 1.31.
Homologues: Orthologues: chimpanzee DEFB125 (95% identical), macaque DEFB125 (82% identical), dog DEFB125 (38% identical), pig DEFB125 (35% identical), mouse Defb26 (32% identical), rat Defb26 (30% identical). Paralogues in human: DEFB129 (19% identical), DEFB118 (17% identical), DEFB127 (17% identical), DEFB132 (15% identical), DEFB123 (14% identical), DEFB121 (13% identical), DEFB119 (13% identical), DEFB124 (12% identical), DEFB128 (12% identical), DEFB135 (12% identical), DEFB108B (11% identical), DEFB108C (11% identical), and 7 more.